BCL2 (BCL2 apoptosis regulator)
Diseases named in the same sentence as BCL2 in open-access papers (continued):
Sharing a sentence is not in itself a finding about the gene and the disease.
gastric cancer (continued). "First, Bcl-2 and Beclin-1 antibodies were immunoprecipitated in DSGOST-treated gastric cancer cells." (PMID 29844404, 2018). "Paeoniflorin modulated MDR against vincristine in human gastric cancer cells SGC7901 partly through inhibition of MDR1, BCL-XL, and BCL-2 expressions." (PMID 30428619, 2018). "Over expression of miR-15 dramatically reduces the expression of BCL2, which reverses the MDR in gastric cancer cells by modulating cell apoptosis." (PMID 29113415, 2017). "This study demonstrates that UA, a naturally occurring triterpenoid, can enhance the antitumor effect of PTX on gastric cancer cells through the down-regulation of COX-2, the decrease of the ratio of Bcl-2/Bax, and the consequent induction of apoptosis." (PMID 29190954, 2017). "miR-503 regulates cisplatin resistance of human gastric cancer cell lines by targeting IGF1R and BCL2." (PMID 32309578, 2016). "miR-1271 regulates cisplatin resistance of human gastric cancer cell lines by targeting IGF1R, IRS1, mTOR, and BCL2." (PMID 32309578, 2016). "Bcl-2 and VEGF expression in the 100-mg S03-EA- and CTX-treated groups were suppressed in the gastric cancer cells." (PMID 25624914, 2015). "The data of qRT-PCR showed significant increase in expression levels of both BCL2 and DNMT3B genes in gastric cancer tissue." (PMID 26172537, 2015). "The effect of S03-EA on the expression levels of Bcl-2, VEGF and Bax was investigated to examine the mechanism behind its inhibition of gastric cancer cell proliferation." (PMID 25624914, 2015). "The study objective was to assess the expression of Bcl-2 and BID in gastric cancer cells in correlation with chosen clinicopathological parameters, presence of Helicobacter pylori infection, and patients' survival." (PMID 24741635, 2014). "In contrast, this miRNA inhibits cell proliferation and colony formation and induces apoptosis in gastric cancer by targeting CREB1 and reduces drug resistance in pancreatic cancer by inhibiting CYLD and BCL-2." (PMID 25299073, 2014). "The correlations between the expression levels of Bcl-2 and BID in gastric cancer cells were found to be statistically insignificant." (PMID 24741635, 2014). "In related studies, we have shown that the chemotherapeutic agent, oxaliplatin, can sensitize gastric cancer cells to TRAIL by regulating components of the apototic/survival machinery such as caspase-3, caspase-8, Bax, and Bcl-2 protein expression." (PMID 24351824, 2013). "Currently, numerous studies have evaluated the prognostic significance of markers, such as the p16, Bcl-2, MTDH and c-myc genes in gastric cancer." (PMID 23599799, 2013). "We have examined the four human gastric cancer cell lines, Kato III, AGS, N87, and MKN45, for their expression levels of Bcl-2 as well as other members of the Bcl-2 family proteins." (PMID 18803879, 2008). "Human gastric cancer cells were transfected with miR-34 mimics or infected with the lentiviral miR-34-MIF expression system, and validated by miR-34 reporter assay using Bcl-2 3'UTR reporter." (PMID 18803879, 2008). "The extracts from P. vulgaris inhibited the proliferation of gastric cancer cells by increasing the levels of BAX and decreasing Bcl-2 levels and suppressed the proliferation of gastric carcinoma by downregulating vascular endothelial growth factor (VEGF) expression." (PMID 38675663, 2024). "The expression levels of Bcl-2 were determined by immunohistochemistry in gastric cancer tissues infected or not with RV." (PMID 37186587, 2023). "The induction of apoptosis is related to BAX overexpression, BCL-2 downregulation, and inhibition of inflammation, as revealed by the downregulation of IL-6, TNF-α, IL-1β, and IL-8 which modulate cell growth proteins in gastric cancer cells." (PMID 36359261, 2022).
gastric cancer (continued). "Additionally, another study showed that the levels of Bcl-2, cyclin A1, and CDK2 were downregulated, and Bax expression was upregulated by overexpression of RSK4 in gastric cancer cells, which is consistent with the results of our study." (PMID 36031631, 2022). "The enrichment included the PI3K-Akt and IL-17 signaling pathways, and the network analysis showed that the Zhishi-Baizhu herb pair acted on seven key targets, namely, AKT1, MMP9, IL-6, CCND1, BCL2, MTOR, and MDM2 (where they played a role in treating gastric cancer)." (PMID 34899944, 2021). "Andrographolide, a labdane diterpenoid from the herb Andrographis paniculata Nees Herba (Acanthaceae), inhibits proliferation and metastasis of gastric cancer SGC-7901 via cell cycle arrest; upregulation of Bax, Bik, and TIMP-1/2; and downregulation of Bcl-2, CD147, MMP-2, and MMP-9." (PMID 34572730, 2021). "Moreover, ginsenoside-Rh2 inhibited proliferation of SGC-7901 side population gastric cancer cells by the induction of cell cycle arrest, as well as cell apoptosis, and altered BAX/Bcl-2 protein expression." (PMID 34572730, 2021). "The Western blot results showed that knocking down of E2F5 decreased the protein expression of E2F5 and BCL2 in gastric cancer cell lines compared with the negative control." (PMID 34947956, 2021). "Similarly, previous results showed that the relative expression of miR-1915-3p was down-regulated in gastric cancer and modulated the development of gastric cancer through the repression of RAGE and BCL-2." (PMID 34774019, 2021). "Moreover, in gastric cancer cells, eupatilin induces apoptosis by regulating apoptotic proteins such as BAX and BCL2 and inducing mitochondrial depolarization." (PMID 34203665, 2021). "In addition, luteolin combined with Oxaliplatin, suppressed proliferation and induced apoptosis in gastric cancer SGC-7901 cells through cleaved caspase-3, upregulated Bax and downregulated Bcl-2." (PMID 34439088, 2021). "Similar studies in glioblastoma, cervical and gastric cancer confirm the role of Rab31 in regulating apoptosis with overexpression of Rab31 correlated with decreased expression of BAX, cleaved caspase 3 and PARP, concomitant with increased expression of BCL-2." (PMID 31973201, 2020). "Further, GHET1 overexpression could prohibit cellular apoptosis by promoting the expression of Bcl-2 and could contribute to the development of multidrug resistance by promoting the expression of MDR1 and MRP1 in gastric cancer." (PMID 32280301, 2020). "Till now, there is no literature discussing the synergic effect between Bcl‐2 inhibitors and chemotherapy in gastric cancer." (PMID 32346976, 2020). "In our study, we found that the combination of BCL2 and MCL1 inhibitors could induce gastric cancer cells more significantly apoptosis." (PMID 33126914, 2020). "HOTAIR has further been found to target miR-34a and activate the PI3K/AKT pathway, consequently decreasing the expression of caspase-3 and BAX, increasing the expression of BCL-2, inhibiting apoptosis, and inducing DDP resistance in gastric cancer cells in vitro and in vivo." (PMID 32460771, 2020). "The present results showed that ZYHT could decrease the expression of Bcl-2 and Cyclin D1, which may be the main mechanism of ZYHT promoting apoptosis and inhibiting proliferation on gastric cancer cells." (PMID 32382534, 2020). "MiR-181b, which is significantly down-regulated in MDR SGC7901/VCR cells, could sensitize gastric cancer cells to VCR and 5-FU through suppressing expression of Bcl-2." (PMID 32192494, 2020). "Furthermore, overexpression of ING3 in gastric cancer cells resulted in apoptosis with increased BAX and CASPASE-3 expression and down-regulated expression of the anti-apoptotic protein BCL2." (PMID 31905726, 2019).
gastric cancer (continued). "In gastric cancer, MEG3 increases Bcl-2 levels by sequestering miR-181-a." (PMID 29641489, 2018). "Conversely, miR-21 is transferred from M2-macrophage to gastric cancer cells through exosomes and inhibits apoptosis of gastric cancer cells by regulating PTEN/phosphoinositide-3-kinase regulatory subunit 1 (Pik3r1, also known as PI3K)/Akt signaling and anti-apoptotic Bcl2 expression." (PMID 29899293, 2018). "Simvastatin, a cholesterol-lowering drug, can sensitize the gastric cancer to the antitumor effects of capecitabine through suppressing the constitutive activation of NF-κB and expression of COX-2, cyclin D1, Bcl-2, survivin, CXC motif receptor 4, and MMP-9 proteins in gastric cancer cells." (PMID 28350359, 2017). "In addition, capsaicin inhibited the proliferation of human gastric cancer cells (AGS cells) and induced apoptosis, via increase of cleaved caspase-3, reduction of Bcl-2, and decrease in the expression of phosphorylated ERK 1/2, p38 MAPK or JNK." (PMID 27529277, 2016). "In addition to suppressing Bcl‐2/Bax ratio, platycodin D has been reported to induce the expression of Bim and c‐Jun through AP‐1 transcriptional activity in AGS gastric cancer cells." (PMID 26648178, 2016). "Specifically, it is necessary to conduct an intensive follow-up plan for gastric cancer patients with negative expression of bcl-2." (PMID 24555747, 2014). "We found positive expression of Bcl-2 in 55.7% and BID in 53.6% of patients with gastric cancer." (PMID 24741635, 2014). "Based on our results, it is possible that via the upregulation of Cyclin D1, EGFR, Bcl-2, MMP-9 and MMP-2 expression and MVD, CXCR1/2 and their ligands are involved in mediating proliferation, growth, angiogenesis, invasion and metastasis of gastric carcinoma." (PMID 23420470, 2013). "Correlation analysis between CXCR1/2 and pAKT (P=0.032), pERK (P<0.001), Cyclin D1 (P=0.049), EGFR (P=0.013), Bcl-2 (P=0.003), microvessel density (P=0.001), MMP-9 (P=0.013) and MMP-2 (P=0.027) expression using the Spearman test showed significant correlation in gastric carcinoma." (PMID 23420470, 2013). "Next, we examined SIRT1, ATF4, MDR1, MRP, Bcl-2, and Bax expression levels after 24 hours' incubation with or without the indicated doses of EX-527 in the gastric cancer cells used above." (PMID 22363646, 2012). "According to the 7th UICC TNM classification, each stage of gastric cancer was further divided into bcl-2 positive and bcl-2 negative group." (PMID 22216342, 2011). "Arsenic trioxide induces apoptosis through induction of Bcl-2 conformational change, Bax activation and up-regulation of total Bax expression rather than affecting total Bcl-2 expression in human gastric cancer SGC7901 cells." (PMID 20403207, 2010). "In summary, SS-a promotes the apoptosis of gastric cancer (GC) cells and suppresses their proliferation by inhibiting the PI3K-AKT signaling pathway and regulating the levels of Bax and Bcl-2 proteins." (PMID 41011202, 2025).
gastric cancer (continued). "Ultimately, CM-DOP inhibited the migration of gastric cancer cells by reversing the effects of N-cadherin and vimentin, as well as increasing the E-cadherin expression; meanwhile, CM-DOP upregulated Caspase-3 and increased the ratio of Bax/Bcl-2, thereby inducing apoptosis." (PMID 37894541, 2023). "Studies have reported that a novel ceRNA activity of lncRNA MEG3 in human gastric cancer cells, lncRNA MEG3 inhibits the cell proliferation, migration and invasion in gastric cancer by competitively binding the miR-181 family, upregulating Bcl-2, and suppressing gastric carcinogenesis." (PMID 35913967, 2022). "In gastric cancer cells, irigenin sensitizes TNF-related apoptosis-inducing ligand (TRAIL)-induced apoptosis by enhancing the expression of pro-apoptotic molecules in the cells, as evidenced by elevated expression of Bcl-2, Caspase-3, and Caspase-8, and in order to make TRAIL produce ROS." (PMID 36532767, 2022). "Moreover, Hesperidin (100 μM) could change cell morphology i,e, chromatin condensation, and apoptosis markers like alter Bcl-2, caspase-3 activation in SNU-668 human gastric cells possible usage of hesperidin in gastric cancer patients." (PMID 35128104, 2022). "MNX1-AS1 activated by TEAD4 can promote the GC process through EZH2/BTG2 and miR-6785-5p/BCL2 axes, suggesting that it was a novel and effective therapeutic target for gastric cancer." (PMID 34712264, 2021). "In the present study, we also found that narciclasine could promote the apoptosis of gastric cancer cells, inhibit the expression of Bcl-2 and increase the expression of Bax, cleaved-PARP and cleaved-3,8,9, suggesting that narciclasine may activate the apoptosis pathway in gastric cancer cells." (PMID 34753517, 2021). "Therefore, Bcl-2 and CCNE1 might contribute to the tumor promoting role of the NUDT21/SGPP2 pathway in gastric cancer cells." (PMID 34660260, 2021). "Additionally, oncogenic lncRNAs MALAT1 and PVT-1 could contribute to 5-FU resistance of gastric cancer by modulating expression of the miR-23b-3p/ATG12 axis and Bcl-2, respectively." (PMID 32192494, 2020). "Additionally, HOXA10 might promote cell proliferation by elevating Bcl-2 expression and inhibiting apoptosis in gastric cancer, and high expression of HOXA10 predicted poor overall survival in gastric cancer patients." (PMID 32296636, 2020). "Taken together, we demonstrate for the first time that the cytomegalovirus protein UL138 could act as anti-oncogene and specifically induce apoptosis of gastric cancer cells by partially interacting with HSP70 and subsequently decreasing Bcl-2 and inducing caspase-3 cleavage." (PMID 26735338, 2016). "Similarly, the results of the present study indicate that ursolic acid may induce apoptosis by decreasing the expression of Bcl-2 and increasing the expression of Bax in SNU-484 gastric cancer cells." (PMID 25621065, 2015). "By contrast, bcl-2 expression did not change in almost all four gastric cancer cell lines." (PMID 25033286, 2014). "However, the Bcl-2/Bax ratio, which was up-regulated in the ATF4-overexpressing cells, was SIRT1-independent, suggesting that SIRT1-independent mechanisms also play a role in the ATF4-induced MDR in gastric cancer cells." (PMID 22363646, 2012). "Thus, Bcl-2 conformational change, Bax activation and up-regulation of total Bax expression involved arsenic trioxide-induced apoptosis rather than affecting total Bcl-2 expression in human gastric cancer SGC7901 cells." (PMID 20403207, 2010).
gastric cancer (continued). "The mechanism of miR-34-mediated suppression of self-renewal appears to be related to the direct modulation of downstream targets Bcl-2, Notch, and HMGA2, indicating that miR-34 may be involved in gastric cancer stem cell self-renewal/differentiation decision-making." (PMID 18803879, 2008). "The mechanism of miR-34-mediated suppression of self-renewal might be related to the direct modulation of downstream targets Bcl-2, Notch, and HMGA2, indicating that miR-34 may be involved in gastric cancer stem cell self-renewal/differentiation decision-making." (PMID 18803879, 2008). "However, for gastric cancer MKN-45 cells that have a low level of Bcl-2 and a high level of miR-34, miR-34 restoration showed no chemosensitization." (PMID 18803879, 2008). "Additionally, a study on human gastric cancer (SGC7901 cells) revealed that betulin prevented cell proliferation and clonogenic growth of gastric cancer cells via activation of intrinsic apoptotic signaling axis by downregulating anti-apoptosis proteins XIAP and Bcl-2." (PMID 37509141, 2023). "Zhang previously reported that the inhibitory effect of DOP on gastric cancer SGC-7901 xenograft tumors in nude mice may be attributed to an elevation in TNF-a and IL-2 levels, as well as the upregulation of Bax and the downregulation of the Bcl-2 protein expression." (PMID 37894541, 2023). "Thus, the majority of gastric carcinomas (if not all) are immunohistochemically negative for bcl-2." (PMID 16759362, 2006). "In gastric cancer (GC), SIRT1 silencing or inhibiting its activity by EX527 enhances expression of FOXO1, pro-apoptotic BAX, and E-cadherin, whereas the expression of Ki67, Cyclin D1, anti-apoptotic Bcl-2, Vimentin, MMP-2 and MMP-9 are downregulated, suggesting SIRT1 involvement in GC progression." (PMID 34769241, 2021). "There is still a lack of predictive indicators for GC recurrence, therefore, the determination of such factors, like it was performed for bcl-2 expression, might be applicable after curative resection in patients with gastric cancer." (PMID 29867026, 2018). "Our data demonstrate that lack of Bcl-2 expression, which is common in gastric cancer, is also frequently found in atrophic gastritis and intestinal metaplasia in mucosa adjacent to GC and may indicate a field of cancerisation, in which gastric cancer can arise." (PMID 28662697, 2017). "In the current study, we found Lin28 were not relevant with Bcl-2, NF-kB and TOPO II in gastric cancer cells." (PMID 26636340, 2015).